IGFBP6 (insulin like growth factor binding protein 6)
Description:
IGF-binding proteins prolong the half-life of the IGFs and have been shown to either inhibit or stimulate the growth promoting effects of the IGFs on cell culture. They alter the interaction of IGFs with their cell surface receptors. Activates the MAPK signaling pathway and induces cell migration.
Synonyms: IBP6
Tractability: Small molecule: it belongs to a druggable protein family. Antibody: UniProt places it where antibodies can reach, with high confidence; its Gene Ontology location is reachable by antibodies, with high confidence; UniProt predicts a signal peptide or a membrane-spanning region. PROTAC: a small molecule that binds it is known.
Target class: Secreted protein
Gene: Protein-coding gene on chromosome 12 (53,097,436 to 53,102,345, forward strand). Ensembl gene ENSG00000167779.
Subcellular location: Secreted
Pathways (Reactome):
Metabolism of proteins: Regulation of Insulin-like Growth Factor (IGF) transport and uptake by Insulin-like Growth Factor Binding Proteins (IGFBPs)
Gene Ontology:
Molecular function: identical protein binding; insulin-like growth factor II binding; protein binding; fibronectin binding; insulin-like growth factor I binding; signaling receptor binding; insulin-like growth factor binding
Biological process: cell migration; positive regulation of MAPK cascade; positive regulation of stress-activated MAPK cascade; negative regulation of canonical Wnt signaling pathway; negative regulation of cell population proliferation; regulation of insulin-like growth factor receptor signaling pathway; signal transduction
Cellular component: insulin-like growth factor binary complex; extracellular region; non-collagenous component of interstitial matrix
Genetic constraint (gnomAD): Loss-of-function variants: 26 observed, 25.11 expected, observed/expected ratio (o/e) 1.04, 90% interval 0.76 to 1.44. The synonymous counts are far from expectation, so gnomAD's model fits this gene poorly and the ratio says little. Missense variants: 331 observed, 285.61 expected, observed/expected ratio (o/e) 1.16, 90% interval 1.06 to 1.27. Synonymous variants: 147 observed, 114.48 expected, observed/expected ratio (o/e) 1.28, 90% interval 1.12 to 1.47.
Homologues: Orthologues: chimpanzee IGFBP6 (99% identical), macaque IGFBP6 (95% identical), pig IGFBP6 (83% identical), guinea pig IGFBP6 (78% identical), rabbit IGFBP6 (75% identical), mouse Igfbp6 (70% identical), rat Igfbp6 (63% identical), zebrafish igfbp6b (32% identical), zebrafish igfbp6a (30% identical). Paralogues in human: IGFBP2 (35% identical), IGFBP5 (35% identical), IGFBP3 (34% identical), IGFBP4 (28% identical), IGFBP1 (28% identical).
Diseases named in the same sentence as IGFBP6 in open-access papers:
IGFBP6 is named in the same sentence as 137 diseases in open-access papers, as found by Europe PMC text mining. Sharing a sentence is not in itself a finding about the gene and the disease. The quoted sentences say what the papers report.
breast cancer (20 papers, 2011 to 2026). A primary or metastatic malignant neoplasm involving the breast. "Kaplan Meier analysis indicates that high IGFBP-6 expression is associated with improved outcomes for patients with PR+ breast cancer." (PMID 39698031, 2024). "It was also found that a decrease in the expression of either IGFBP6 or ELOVL5 gene increases sensitivity of MDA-MB-231 breast cancer cells to LC-PUFAs and our data suggest that they cause cell death by activation of ferroptosis." (PMID 36714261, 2023). "Here we dissect regulatory subnetwork centered on IGFBP6 gene, which is associated with low proliferative state and high migratory activity of basal-like breast cancer." (PMID 31781574, 2019). "In this paper we concentrate on a dissection of a particular regulatory subnetwork centered on IGFBP6 gene, which is associated with low proliferative state and high migratory activity of basal-like breast cancer." (PMID 31781574, 2019). "Since IGFBP-6 induction is associated with conditions in which cell proliferation is repressed it was hypothesized that IGFBP-6 has a role in slowing breast cancer cell proliferation." (PMID 39698031, 2024). "Overexpression of IGFBP6 is associated with a better prognosis in breast cancer." (PMID 37088808, 2023). "Cell cycle analysis showed that IGFBP-6 knockdown in Hormone Receptor Positive T47D breast cancer cells resulted in an increased number of cells in the G1 phase and a decrease in cells in G2, indicating a role for IGFBP-6 in cell cycle regulation." (PMID 41419198, 2025). "Taken together, our results demonstrate that IGFBP-6 regulates cell cycle progression in breast cancer cells and interferon signaling in hormone-positive cells." (PMID 41419198, 2025). "Previous studies have demonstrated that survival outcomes are improved by IGFBP-6 for patients with breast cancer." (PMID 39698031, 2024). "In this study, survival analysis demonstrated that high IGFBP-6 improved overall survival in PR positive breast cancer patients." (PMID 39698031, 2024). "Previously, it was shown that the MDA-MB-231 breast cancer cells knockdown for IGFBP6, MDA-MB-231IGFBP6, has an increased level of proliferation and higher metastatic potential compared to control." (PMID 39480639, 2024). "Survival analysis using available databases indicated that high IGFBP-6 levels improve overall survival in progesterone receptor positive breast cancers." (PMID 39698031, 2024). "IGFBP-6 is transcriptionally induced by progesterone in T47D breast cancer cells resulting in increased intracellular and extracellular IGFBP-6 protein." (PMID 39698031, 2024). "In T47D breast cancer cells, P4 induced IGFBP-6 transcriptionally and was inhibited by treatment with mifepristone (RU 486)." (PMID 39698031, 2024). "The RNA-seq data shows that patients with PR+ breast cancer had improved overall survival when IGFBP-6 was above the median in both data sets." (PMID 39698031, 2024). "In this work, we studied the effect of viscumin on MDA-MB-231 breast cancer cells with IGFBP6 gene knockdown." (PMID 39480639, 2024). "Our results indicate that IGFBP-6 is induced by progesterone in T47D breast cancer cells and stabilizes progesterone receptor levels." (PMID 39698031, 2024). "Reduced expression of the IGFBP6 protein leads to an increase in the metastatic potential of breast cancer (BC) cells." (PMID 39480639, 2024). "Contrary to the results presented above, a study related the low expression of ELOVL5 and insulin-like growth factor binding protein 6 (IGFBP6) with pronounced metastasis in breast cancer." (PMID 36970499, 2023). "As expected, breast cancer cells after the knockdown of either ELOVL5 or IGFBP6 gene were more sensitive to DHA (p < 0.05)." (PMID 36714261, 2023). "The reason why the breast cancer cells with reduced expression of either ELOVL5 or IGFBP6 gene are more sensitive to ferroptosis is complex." (PMID 36714261, 2023).
breast cancer (continued). "Previously we have shown that low expression of ELOVL5 and IGFBP6 genes in breast cancer tissue corresponded to poor prognosis." (PMID 36714261, 2023). "All described changes suggest that IGFBP6 can be involved in the regulation of lipid metabolism in breast cancer cells." (PMID 36714261, 2023). "Inhibition of the ELOVL5 and IGFBP6 genes in breast cancer cells results in the increased expression of matrix metalloproteinase 1 and reduction of intercellular contacts." (PMID 36970499, 2023). "Next, we examined properties of breast cancer cells related to metastatic propensity after the knockdown of either ELOVL5 or IGFBP6 gene." (PMID 36714261, 2023). "In this study, we focused on the role of ELOVL5 and IGFBP6 genes in the metabolism of LC-PUFAs in breast cancer cells." (PMID 36714261, 2023). "In all, our data demonstrate that reduction in the expression of ELOVL5 or IGFBP6 genes can lead to an increase in the sensitivity of breast cancer cells to various PUFAs." (PMID 36714261, 2023). "IGFBP6 expression was found to be lower in gastric cancer, nasopharyngeal cancer, colon cancer and breast cancer." (PMID 37088808, 2023). "Fibroblast growth factor-2 and IGFBP-6 are both activated in breast cancer by Vasohibin-2, an angiogenic factor." (PMID 35457175, 2022). "In this study, the relationship between GPR81 and IGFBP6 protein in tumor growth and oxidative stress in the human breast cancer cell line MDA-MB-231 was studied." (PMID 35204157, 2022). "After c-Myc activation, the decrease of IGFBP-6 significantly enhances fibroblast activation and mobilization and increases the chemotactic potency of human primary breast cancer fibroblasts." (PMID 35457175, 2022). "The present data highlighted the relevance of the lactate-induced GPR81/IGFBP6 crosstalk in tumor progression in MDA-MB-231 breast cancer cells." (PMID 35204157, 2022). "Future studies focused on in vitro and in vivo models of breast cancers are needed to highlight the role of the GPR81/IGFBP6 axis in additional cell lines, homocellular the heterocellular communication, and metabolic signaling of the tumor microenvironment." (PMID 35204157, 2022). "Then, to investigate the existence of an axis between lactate, MCT1-4 receptors and IGFBP6, the breast cancer cells were exposed to the recombinant protein IGFBP6 for 24 h." (PMID 35204157, 2022). "Consistently, our data showed that the treatment of breast cancer cells with IGFBP6 significantly induced an increase in the mRNA expression of the LDHA, MCT1 and MCT4 genes." (PMID 35204157, 2022). "In a previous study, shRNA based suppression of IGFBP6 in basal-like breast cancer cell line MDA-MB-231 led to a notable inhibition of cell migration along with an increase in its rate of proliferation." (PMID 31781574, 2019). "Taken together, observations concerning LAMA4, its regulating miRNA miR-4274 and its host gene SORCS2, point at a substantial role played by secondary and tertiary effects produced by a transcriptional knockdown of IGFBP6 in basal-like breast carcinoma cells." (PMID 31781574, 2019). "Serum IGFBP6 concentrations were lower in breast cancer patients as compared to those with benign breast disease." (PMID 27623076, 2016). "Interestingly, in breast cancer, where elevated IGFBP-6 correlates with improved survival, TCGA analysis found that IGFBP-6 expression also positively correlated with CD4+ and CD8+ T-cell and macrophage infiltration into the tumor microenvironment (TME)." (PMID 41226289, 2025). "Thus, our results suggest that IGFBP6 can play an important role in the regulation of lipid metabolism in breast cancer cells." (PMID 36714261, 2023). "Thus, for the breast cancer patients with low expression of IGFBP6 and ELOVL5 genes in cancer tissue the addition of PUFAs to the chemotherapy regimen can be potentially beneficial and should be tested in more clinically relevant settings." (PMID 36714261, 2023).
breast cancer (continued). "Thus, the reduction in the expression of ELOVL5 or IGFBP6 genes leads to increased sensitivity to the induction of ferroptosis in breast cancer cells and at the same time makes them more responsive to its inhibition." (PMID 36714261, 2023). "Next, we tested whether the expression of GPX4 gene can also decrease simultaneously with the expression of IGFBP6 gene in breast cancer tissue." (PMID 36714261, 2023). "Thus, in this work we studied the changes in lipid metabolism in breast cancer cells with reduced expression of either ELOVL5 or IGFBP6 gene." (PMID 36714261, 2023). "Indeed, it was demonstrated that IGFBP-6 improves mitochondrial fitness and redox, reducing mitochondrial ROS production and modulating lactate metabolism and oxidative stress in a human breast cancer cell line." (PMID 35457175, 2022). "We inhibited expression of IGFBP6 gene in a model cell line for basal-like breast carcinoma MDA-MB-231, then traced secondary and tertiary effects of this knockdown to LAMA4, a laminin encoding gene that contributes to the phenotype of triple-negative breast cancer." (PMID 31781574, 2019). "Analysis of spheroid formation confirmed that intercellular adhesion decreased as a result of both ELOVL5 and IGFBP6 knockdowns, thus suggesting that malignant breast tumors with reduced expression of ELOVL5 or IGFBP6 gene may metastasize more actively due to more efficient tumor cell invasion." (PMID 36714261, 2023). "In conclusion, our data support the role of lactate metabolism in breast cancer, highlighting a new pathway activated by glucose metabolism in the tumor microenvironment, i.e., the activation of GPR81/IGFBP6 crosstalk, which may represent a new therapeutic target in breast cancer." (PMID 35204157, 2022). "In contrast, Insulin-like growth factor-binding protein 6 (IGFBP6) has low frequency in both colon and breast cancers." (PMID 41516087, 2025). "Our data showed that lactate induced cell proliferation and wound healing of the MDA-231 breast cancer cell through the overexpression of both the lactate receptor GPR81 and IGFBP6." (PMID 35204157, 2022). "While the contribution of the IGF-signaling axis in breast cancer is well-documented, the role of IGFBP-6 in breast carcinogenesis has not been extensively studied." (PMID 41419198, 2025). "There was no significant improvement in overall survival from high IGFBP-6 in ER+, PR- breast cancer patients." (PMID 39698031, 2024). "Survival analysis demonstrates that ER positive, PR negative breast cancers have no benefit in overall survival from IGFBP6." (PMID 39698031, 2024). "IGFBP-6 provides no significant benefit in ER+ but PR- breast cancers suggesting that IGFBP-6 provides a benefit when PR is high." (PMID 39698031, 2024). "Finally, a recent study identified a relationship between the GPR81 lactate receptor and the IGFBP6 protein, which is able to modulate lactate metabolism and oxidative stress in human MDA-MB-231 cells, thus influencing breast cancer growth." (PMID 36714261, 2023). "Thus, the obtained data indicate that malignant breast tumors with reduced expression of the ELOVL5 and IGFBP6 genes can metastasize with a higher probability due to a more efficient invasion of tumor cells." (PMID 34149804, 2021). "IGFBP6 inhibits growth in a number of IGF-II-dependent cancers, including rhabdomyosarcoma, neuroblastoma, colon cancer, lung cancer, prostate cancer, breast cancer and ovarian cancer." (PMID 27623076, 2016). "However, the role of IGFBP-6 in breast cancer is not well defined." (PMID 39698031, 2024).
glioblastoma (11 papers, 2015 to 2025). The most malignant astrocytic tumor (WHO grade IV). "We confirmed the diagnostic ability of IGFBP6 to discriminate the glioblastoma patients from healthy subjects (AUC = 0.826, P < 0.0001) or from the patients affected to astrocytoma (AUC = 0.753, P < 0.0001) or oligodendrocytoma (AUC = 0.748, P < 0.0001)." (PMID 35654889, 2023). "Specifically, patients with glioblastoma expressed significantly higher levels of the IGFBP6 messenger in the brain than patients with oligodendroglioma (P < 0.0001), astrocytoma (P < 0.0001), or healthy subjects (P < 0.0001)." (PMID 35654889, 2023). "Through paracrine IGF2/IGF-1R signaling, IGFBP6 regulates the growth of chemoresistant glioblastoma, which is produced by scilicet chemosensitive tumor cells, and is secreted, which slows the evolution of GBM." (PMID 36865549, 2023). "IGFBP6 had the highest proportion of mRNA (94%) expressed in glioma cell lines that were derived from primary glioblastomas, and the biological function study showed that IGFBP6 is an unfavorable prognostic factor of patients with glioma." (PMID 35832140, 2022). "Moreover, an acidic environment upregulates insulin-like growth factor binding protein 6 expression, consequently facilitating immune evasion in glioblastoma." (PMID 40722682, 2025). "IGFBP6 is involved in migration, immune escape and inflammation in glioblastoma." (PMID 37088808, 2023). "Furthermore, our results showed that IGFBP6 discriminated patients with glioblastoma versus those with astrocytoma and oligodendroglioma." (PMID 35654889, 2023). "The IGFBP6 gene expression analysis obtained from the GSE108474 dataset showed that there were significant differences when the expression levels obtained from brain biopsies of glioblastoma patients were compared to the other brain tumors stages." (PMID 35654889, 2023). "By carrying out a Pearson correlation analysis between IGFBP6 and IDH1 brain tumor expression levels, we highlighted that in glioblastoma patients, the expression levels of the two genes were significantly closely inversely correlated (r = -0.3743, P < 0.0001)." (PMID 35654889, 2023). "Interestingly, there exists an inverse correlation between IGFBP6 and IDH1 expression in glioblastoma patients." (PMID 35654889, 2023). "For example, STCs exhibited, compared to STPs, the overexpression of several markers of the mesenchymal subtype of glioblastoma, such as COL1A1, COL1A2, COL5A1, IGFBP6, DCBLD2, many of which are also typically expressed by microglia or reactive astrocytes in glioblastoma microenvironment." (PMID 26188123, 2015). "Consistent with our data, it has been reported that administration of exogenous IGFBP6 plays a tumor suppressive role in PT-resistant, but not PT-sensitive, EOC cells and that IGFBP6 expression is reduced in chemo-resistant glioblastoma." (PMID 38658801, 2024).